GSK3B (glycogen synthase kinase 3 beta)
Diseases named in the same sentence as GSK3B in open-access papers (continued):
Sharing a sentence is not in itself a finding about the gene and the disease.
schizophrenia (continued). "It is widely known that NMDARs activate primary signaling cascades including PI3 kinase-Akt-GSK-3β and Ras-MAPK kinase (MEK)-MAPK signaling pathways, both of which are involved in the pathogenesis of schizophrenia and the therapeutic mechanisms of antipsychotic agents." (PMID 34054433, 2021). "Interestingly, CREB is a substrate for Akt and GSK3β phosphorylation: Akt at Ser133, while GSK3β at Ser129; and besides these studies that implicate CREB in schizophrenia, evidence is provided by patients’ postmortem pathological studies." (PMID 30214393, 2018). "Additionally, AKT protein levels and phosphorylation of GSK3β are altered and NRG1-stimulated phosphorylation of AKT is reduced in schizophrenia." (PMID 23543703, 2013). "Conversely, other reports detected no changes in GSK-3β mRNA levels in blood cells obtained from first-episode schizophrenia patients, and the levels of the protein were actually low in the frontal cortex and CSF of schizophrenia subjects." (PMID 35126052, 2021). "We found that clozapine combining with PQQ treatments could ameliorate the memory deficits in MK-801 induced schizophrenia rats partially by reducing the expression of NMDAR1 and MGLUR3, decreasing hippocampal tau hyperphosphorylation and inhibiting apoptosis through GSK-3β/Akt signaling pathway." (PMID 32143671, 2020). "To go through this hypothesis, we quantified the protein expression and phosphorylation of the mTOR downstream effector ribosomal protein S6 as well as other pathway interactors such as Akt and GSK3β, in postmortem PFC from subjects with schizophrenia and control subjects." (PMID 32265715, 2020). "Intriguingly, a protein-protein interaction between D2R and DISC1 (disrupted in schizophrenia 1) was identified as a candidate initiator of hyperactive behaviors in mice that require βarr2 signaling to regulate AKT phosphorylation and subsequent GSK3β activation." (PMID 31261897, 2019). "Since prefrontal dysfunction is linked to the negative symptoms of schizophrenia, it is suggested that suppression of GSK3β function in the PFC is very likely to contribute to the effects of aripiprazole on the negative symptoms of schizophrenia, which cannot be achieved by haloperidol." (PMID 27043526, 2016). "Furthermore, we found that modulating NMDA receptors could ameliorate the memory impairments in Mk-801 induced schizophrenia rats by reducing the expression of NMDAR1 and MGLUR3, decreasing hippocampal tau hyperphosphorylation and inhibiting apoptosis through Akt /GSK-3β signaling pathway." (PMID 32143671, 2020). "However, whether aripiprazole can affect GSK3β activity in other schizophrenia-related brain regions has not yet been studied." (PMID 27043526, 2016). "PIK4CA expression was lower, whereas Akt expression was higher, in the PFC of schizophrenia patients than in that of controls; PIP5K1C, PTEN, and GSK3β expression was not different." (PMID 34361045, 2021). "However, at the single time point studied here, there was no change in hippocampal expression or phosphorylation of JNK or p38 themselves, nor of proteins such as 14-3-3ε, c-Jun, GSK-3β, β-Catenin and HSP90 which have been associated with schizophrenia and may represent additional treatment targets." (PMID 29423817, 2018). "Another study showed increased inhibitory phosphorylation of GSK3β and β-catenin, but no significant changes in mRNA or protein levels in PFC and VTA of rats treated with MK-801, an NMDA glutamate-receptor antagonist which induces schizophrenia-like behaviours." (PMID 24403877, 2013).
ovarian carcinoma (89 papers, 2003 to 2026). A malignant neoplasm originating from the surface ovarian epithelium. "Glycogen synthase kinase-3 beta (GSK3B) is a glycogen metabolism enzyme that upregulates NF-κB activity, a key driver of proliferation and survival in ovarian cancer cells, and inhibition of GSK3B caused tumor shrinkage in mice." (PMID 32698955, 2020). "Yet, in ovarian cancer, GSK3B activity was linked with cell proliferation, and overexpression of its active form can induce CDK1 expression and facilitate cell proliferation." (PMID 31108958, 2019). "In ovarian cancer cells, βArr1 is linked with the endothelin-1-induced activation of Akt, GSK-3β in integrin-linked kinase (ILK) activation." (PMID 23418490, 2013). "In triple-negative breast cancer, downregulation of circ-ITCH lifts repression on miR-17 and miR-214, enhancing pathway activation, and in ovarian cancer, loss of circFBXO7 promotes β-catenin accumulation and Glycogen Synthase Kinase 3 Beta (GSK3β) phosphorylation." (PMID 41050070, 2025). "It was then postulated that GSK3β phosphorylation may be linked to the high frequency of activating mutations in PI3K in ovarian cancers." (PMID 31829231, 2019). "In this relatively small clinical cohort, we found that levels of GSK3β transcripts were significantly higher in patients with ovarian cancer–associated recurrence (p < 0.05 vs. incidence free) and in patients who died of ovarian cancer (p < 0.05 vs. patients who are alive) (respectively)." (PMID 28930226, 2017). "In ovarian cancer, Wnt/β-catenin signaling might be activated by increased expression of β-catenin and glycogen synthase kinase 3β (GSK3β), mutations of catenin beta 1 (CTNNB1) gene, and so on." (PMID 27708548, 2016). "Triptolide has been demonstrated in ovarian cancer cell lines and animal models to reduce ovarian cancer chemoresistance by interrupting PI3K/AKT/GSK3‐β and JAK/STAT3 signaling pathways." (PMID 40968783, 2026). "Subsequently, we validated the PI3K/AKT signaling pathway, a key pathway for CE action in ovarian cancer, and found the core target GSK3B as downstream of PI3K/AKT at the KEGG website." (PMID 40071097, 2025). "In particular, hyptolide inhibits the activity of β-catenin and increases the expression of E-cadherin by activating GSK3β in cisplatin-resistant ovarian cancer cells." (PMID 40506749, 2025). "Resveratrol decreased hexosamine production in ovarian cancer cells, disrupted protein glycosylation by stimulating glycogen-synthase kinase 3β (GSK3β), or led to ER stress-induced death." (PMID 40868085, 2025). "Western blot results showed that the expression of P-PI3K/PI3K, P-AKT/AKT and P-GSK3B/GSK3B were reduced in ovarian cancer cells in the CE-treated group compared with the control group." (PMID 40071097, 2025). "At the same time, higher protein levels of CXCL8, p-GSK-3β (Ser9), and p-p70S6K (Thr389) were found in ovarian cancer tissues." (PMID 39660100, 2025). "Mechanistically, we found that VII can bind to RORα, enhance its protein stability, and inhibit the FAK/AKT/GSK3β signaling pathway in ovarian cancer cells resistant to PARP inhibitors through the RORα/ECM1/VEGFR2 signaling axis." (PMID 38725854, 2024). "The results showed that ECM1 can rescue the expression levels of p-FAK, p-AKT, and p-GSK3β in PARP inhibitor-resistant ovarian cancer cells." (PMID 38725854, 2024). "This regulatory mechanism influences the Akt/GSK-3B/Snail signaling pathway, contributing to the control of ovarian cancer proliferation." (PMID 38793064, 2024). "Selenium-enriched polysaccharides from Pyracantha fortuneana were found to inhibit β-catenin signaling in a GSK-3β-dependent mechanism to reduce the growth and invasion of human ovarian cancer cells." (PMID 38289713, 2024). "A dual inhibitor targeting GSK3B and histone deacetylases (HDACs) slowed tumor growth in mouse pancreatic and ovarian cancer models." (PMID 39166606, 2024).
ovarian carcinoma (continued). "Consistent with our findings, lactate production was inhibited by blocking AKT1/GSK3β (glycogen synthase kinase 3 beta) signaling in ovarian cancer cells after treatment with the VEGFR2 kinase inhibitor apatinib." (PMID 38396845, 2024). "Cyclin D1 degradation has been reported to occur through the AMPK/GSK3β signaling axis through the proteasome pathway in ovarian cancer cells." (PMID 35411000, 2022). "High levels of miR-29a-3p expression inhibit PD-L1 expression in ovarian cancer cells by downregulating the FOXO3-AKT/GSK3β axis, leading to immune escape of OC cells and ultimately promoting the proliferation of ovarian cancer cells." (PMID 36741380, 2022). "The GSK-3β inhibitor AZD1080 suppresses ovarian cancer cell proliferation, invasion, and migration and downregulates GSK-3β, MMP9, and Bcl-xL mRNA and proteins." (PMID 35723293, 2022). "Emodin, for example, inhibits ovarian cancer SKOV3 cell invasion by inhibiting EMT by regulating the GSK-3β/β-catenin/ZEB1 signaling pathway." (PMID 35035481, 2022). "Other transcripts included AKT3 and GSK3β, coding for the variable 3 of protein kinase b and for Glycogen synthase kinase 3 beta, respectively; both factors induce cell proliferation and migration in ovarian carcinoma cells." (PMID 35562985, 2022). "miR-203a has been shown to hinder the proliferation, migration and invasion of ovarian cancer cells through modulation of the AkT/GSK-3β/Snail signaling pathway." (PMID 35530324, 2022). "Suppressing Hsp90 chemosensitized multi-drug resistant ovarian cancer cells via impairing the AKT/GSK3β/β-catenin signaling, providing a promising therapeutic strategy for a successful treatment of ovarian cancer." (PMID 33738259, 2021). "In conclusion, Hsp90 enhanced the AKT/GSK3β/β-catenin signaling to induce multi-drug resistance of ovarian cancer." (PMID 33738259, 2021). "Suppressing Hsp90 re-sensitized multi-drug resistant ovarian cancer cells via downregulating AKT/GSK3β/β-catenin signaling." (PMID 33738259, 2021). "Knockdown of endogenous GSK3β in ovarian cancer cells inhibited both phospho-ETS1 and MMP-9 expression." (PMID 34023818, 2021). "The treatment with LiCl also caused a decrease in cell number, which led to the conclusion that GSK3β promotes ovarian cancer cell proliferation and tumor growth." (PMID 32767962, 2021). "Both p-GSK-3β and β-catenin were found to be upregulated in ovarian tumors, implying they perform a positive role in the progression of ovarian cancer." (PMID 34065149, 2021). "One study also assessed the expression of the active form pGSK3β-Y216 and found its overexpression as well, which led to the conclusion that GSK3β is both overexpressed and overactivated in ovarian cancer cells." (PMID 32767962, 2021). "Paris saponin VII impeded ovarian cancer cell migration and invasion by regulating the GSK-3β pathway." (PMID 34955834, 2021). "Ovarian cancer cells resistant to cisplatin had similar overall expression of GSK3β and of pGSK3β-Y216, but significantly lower expression of silenced pGSK3β-S9 in comparison to the source cell line." (PMID 32767962, 2021). "Triptolide also indirectly inhibits NF-ĸB signaling through the AKT/GSK3β/mTOR pathway and induces apoptosis in ovarian cancer by inhibition of NF-ĸB expression." (PMID 34213719, 2021). "We conclude that the GSK3β/ETS1/MMP-9 axis regulates the biological aggressiveness of ovarian cancer." (PMID 34023818, 2021). "In this study, we investigated the effect of first-in-class dual inhibitor agents of GSK3B and HDACs for the treatment of ovarian cancer." (PMID 32698955, 2020).
ovarian carcinoma (continued). "In ovarian cancer cells, resveratrol inhibited the biosynthesis of hexosamine, and interrupted protein glycosylation through activating glycogen synthase kinase-3β (GSK3β), and eventually triggered ER stress-mediated apoptosis." (PMID 32934709, 2020). "Our results showed that dual inhibition of GSK3B and HDACs significantly reduced cancer cell survival both in human and mouse ovarian cancer cell lines." (PMID 32698955, 2020). "Results also demonstrated that regulation of the glycogen synthase kinase 3 beta (GSK3β)/β-catenin signaling pathway promotes the development of ovarian cancer." (PMID 33292213, 2020). "Suppression of GSK-3β activity by GSK3β-specific siRNAs in ovarian cancer BG1 cells resulted in increased Let-7 levels and decreased BG1 survival." (PMID 32365809, 2020). "Studies have shown that ursolic acid (MOL074, OB = 37.73%, DL = O.75) induces apoptosis via activation of caspases and phosphorylation of glycogen synthase kinase 3 beta in ovarian cancer cells." (PMID 31949474, 2019). "We found that daidzein and ERB-041 decreased p-PI3K85, p-AKT, p-GSK3β, and cyclin D1 expression, suggesting PI3K/AKT/GSK3β/cyclin D1 signaling is linked to daidzein and ERB-041 induced G1 cycle arrest in ovarian cancer." (PMID 29743815, 2018). "The study investigated the direct effects of ShenLingLan on ovarian cancer cell behaviour in vitro and investigated the transcript expression profile of GSK-3β in our ovarian cohort." (PMID 28930226, 2017). "Loss of AKT phosphorylation at S473 in mitotically arrested ovarian cancer cells was accompanied by a significant decrease in AKT activity, since the phosphorylation of several downstream targets of AKT, such as GSK3β, PRAS40 and p70S6K, was reduced." (PMID 28152500, 2017). "In contrast, GSK3β overexpression has been observed in ovarian, colon and pancreatic tumours resulting in enhanced proliferation and survival of ovarian cancer cells in vivo and in vitro." (PMID 27907888, 2017). "Downregulation of GSK3β expression level conferred resistance of ovarian cancer cells from cisplatin treatment." (PMID 27195613, 2016). "GSK3B is a negative regulator of Wnt signaling pathway and inhibition of GSK3B activity, i.e. increased p-Ser9, has previously been shown to confer resistance to cisplatin in lung and ovarian cancer cells." (PMID 26353782, 2015). "Downregulation of Twist2 expression facilitated apoptosis and recovered the sensitivity of chemoresistant ovarian cancer through the AKT/GSK-3β pathway." (PMID 24944676, 2014). "And also, GSK-3β was showed as a potential therapeutic target in various cancer involved in pancreatic, colon, renal, prostate, thyroid, ovarian cancer and leukemia." (PMID 25157753, 2014). "Given its low toxicity, Huaier's effect on GSK3β/β-catenin signaling makes it an attractive way to target invasion in epithelial ovarian cancer cells." (PMID 23667667, 2013). "In this study, in addition to its anti-proliferative and apoptotic effects, the novel possibility that Huaier exerts an anti-invasive effect in ovarian cancer cells via the AKT/GSK3β/β-catenin signaling pathway was investigated." (PMID 23667667, 2013). "Using this construct we screened a kinase inhibitor library and discovered that GSK-3β repressed let-7 production in ovarian cancer cells, thus uncovering GSK-3β as a novel target for therapeutic intervention." (PMID 23840442, 2013). "In summary, in addition to inhibiting cell growth by reducing proliferation and inducing apoptosis, Huaier reduces cell mobility in ovarian cancer cells via the AKT/GSK3β/β-catenin signaling pathway." (PMID 23667667, 2013). "KEGG pathway analysis predicted that CE might affect ovarian cancer by regulating the PI3K/AKT/GSK3B pathway." (PMID 40071097, 2025). "Moreover, resveratrol reduced the levels of the extracellular signal-regulating enzyme (ERK) and phosphorylated AKT and GSK3β in ovarian cancer cells in a dose-dependent manner." (PMID 40868085, 2025).
ovarian carcinoma (continued). "However, increased GSK3β activation was observed in chemoresistant ovarian cancer cells with hyptolide treatment." (PMID 40506749, 2025). "In addition, decreased phosphorylation and enhanced stability of β-catenin were observed in BRCA2-null mouse ovarian cancer cells, which correlated with increased inhibitory phosphorylation on GSK3β." (PMID 39028933, 2024). "Although it is verified that GSK3β positively regulates the proliferation of human ovarian cancer cells, the association between GSK3α and ovarian cancer has not been demonstrated." (PMID 38613588, 2024). "Its potential function may hinder glycolysis and angiogenesis in PARPi resistant ovarian cancer cells, which is associated with PS VII binding and stabilizing RORα expression, further inhibiting ECM1 and blocking the VEGFR2/FAK/AKT/GSK3β signaling pathway." (PMID 38725854, 2024). "In an ovarian carcinoma cell line, chlorambucil was observed to mediate a 5-fold reduction in PD-L1 through transcriptional or post-transductional mechanisms, including the promotion of PD-L1 ubiquitination mediated by the GSK3β/β-TRCP signaling pathway." (PMID 39239387, 2024). "Furthermore, when lithium blocks GSK3β activity, ovarian cancer cell proliferation was reduced and tumor suppressor activity was observed in nude mice inoculated with human ovarian cancer cells." (PMID 36836894, 2023). "Besides, exosomes enriched with miR-29a-3p mediate the FOXO3-AKT/GSK3β axis and improve the expression of PD-L1 in ovarian cancer cells, consequently promoting the proliferation and immune escape of ovarian cancer cells." (PMID 35741075, 2022). "On the other hand, both β-catenin and GSK3β were highly expressed in ovarian cancer." (PMID 34329303, 2021). "We conclude that the GSK3β/ETS1/MMP-9 axis may regulate the biological aggressiveness of ovarian cancer and can serve as a prognostic factor in patients with this malignancy." (PMID 34023818, 2021). "It is conceivable that – in addition to the GSK3β/Snail pathway – the GSK3β/ETS1/MMP-9 axis may be involved in ovarian cancer spread." (PMID 34023818, 2021). "Downregulation of miR-186-5p and upregulation of GSK3B have been reported in ovarian carcinoma." (PMID 33133155, 2020). "Also, lncRNA SNHG3 can modulate GSK3β/β‐catenin pathway to regulate the progression of ovarian cancer." (PMID 32248648, 2020). "Though all these three kinases have negative impact on the microtubule assembly activity of CRMP2, FER kinase regulates microtubule assembly via a different mechanism, compared with GSK3β and Rho kinase that are both known to be expressed in ovarian cancer cells." (PMID 29396402, 2018). "Moreover, genistein, daidzein and ERB-041 treatment reduced p-FAK, p-PI3K, p-AKT, p-GSK3β, p21 or cyclin D1 expression in ovarian cancer cells." (PMID 29743815, 2018). "Additionally, GSK3β inhibition suppressed ovarian cancer cell proliferation in vitro and decreased growth and survival of colon cancer cells in vivo." (PMID 27907888, 2017). "Moreover, activation of the Wnt pathway via treatment with a Wnt3a ligand or a GSK3β inhibitor resulted in strong induction of MSX2 expression in ovarian cancer cells." (PMID 27088357, 2016). "Thus, the present study investigated the correlation between the AKT/GSK-3β pathway and Twist2 expression in ovarian cancer." (PMID 24944676, 2014). "GSK3β has been reported to be very important in ovarian cancer." (PMID 23667667, 2013). "In addition to the anti-proliferation and pro-apoptotic effects found in other studies, we have provided evidence that Huaier can inhibit the invasion of ovarian cancer cells via the AKT/GSK3β/β-catenin pathway." (PMID 23667667, 2013).